RRBP1 (ribosome binding protein 1)
Diseases named in the same sentence as RRBP1 in open-access papers (continued):
Sharing a sentence is not in itself a finding about the gene and the disease.
coronary artery disease (1 paper, 2023). "Recent GWASs have linked RRBP1 (ER ribosomal-binding protein 1) genetic variants to intracranial arterial aneurysm, coronary artery disease, cardiovascular disease, and vascular headache." (PMID 36803854, 2023).
endometrial carcinoma (1 paper, 2019). A malignant tumor arising from the epithelium that lines the cavity of the uterine body. "We investigated the expression of RRBP1 protein by immunohistochemistry on paraffin-embedded surgical specimens from one hundred thirty patients with endometrioid-type endometrial carcinoma." (PMID 30684972, 2019). "This study aimed to determine RRBP1 expression in endometrioid-type endometrial carcinoma and to reveal the connection between RRBP1 and the clinical significance of endometrial cancer." (PMID 30684972, 2019). "As far as we known, this is the first study to investigate RRBP1 expression in endometrial carcinoma and normal endometrium tissues." (PMID 30684972, 2019). "We analyzed the association between RRBP1 expression levels and a range of clinicopathologic features including FIGO stage, lymph node metastasis and depth of myometrial in endometrioid-type endometrial carcinoma (EC)." (PMID 30684972, 2019). "We also evaluated the differences in RRBP1 expression between endometrial cancer samples (n = 35) and normal endometrial tissues (n = 19) by western blotting." (PMID 30684972, 2019). "Our purpose is to explore the function of RRBP1 in endometrioid-type endometrial carcinoma." (PMID 30684972, 2019). "RRBP1 may become a useful target for treating endometrial cancer and a marker for identifying patients with poor prognoses." (PMID 30684972, 2019). "RRBP1 was more highly expressed in endometrial cancer samples than in normal samples (P < 0.05)." (PMID 30684972, 2019). "However, the relationship between RRBP1 and endometrioid-type endometrial carcinoma (EC) remains unknown." (PMID 30684972, 2019). "However, the expression and clinical significance of RRBP1 in endometrial carcinoma has not previously been reported." (PMID 30684972, 2019).
epithelial ovarian cancer (1 paper, 2019). "In the present study, the clinicopathological effects of RRBP1 in epithelial ovarian cancer and their association with prognosis were analyzed and validated." (PMID 31285390, 2019). "Western blotting results showed the expression of RRBP1 was excessive at protein level in epithelial ovarian cancer samples (P<0.05)." (PMID 31285390, 2019). "The clinical significance of RRBP1 and its involvement in the epithelial ovarian cancer have yet to be studied." (PMID 31285390, 2019). "Real-time PCR results showed that the expression of RRBP1 at mRNA level in epithelial ovarian cancer tissues is much higher than that in normal epithelial ovarian cancer tissues (P<0.05)." (PMID 31285390, 2019). "The Western blotting and qRT-PCR results confirmed that the expression of RRBP1 in epithelial ovarian cancer tissues was much higher than that in normal tissues." (PMID 31285390, 2019). "The aim of the present study was to investigate the expression of RRBP1 in epithelial ovarian cancer (EOC) and its relationship with clinical characteristics and prognosis." (PMID 31285390, 2019). "The role of RRBP1 in epithelial ovarian cancer was consistent with the results of the current study and proved the connection between the overexpression of RRBP1 in epithelial ovarian cancer and adverse biological behavior." (PMID 31285390, 2019). "Immunohistochemistry and data analysis were used to examine the relationship between the expression level of RRBP1 and the clinicopathological features and prognosis of epithelial ovarian cancer." (PMID 31285390, 2019). "Overexpression of RRBP1 in epithelial ovarian cancer was shown to be obviously related to FIGO stage, histological grade, histological type, and lymph node metastasis." (PMID 31285390, 2019). "In the present study, we examined the expression level of RRBP1 in epithelial ovarian cancer by immunohistochemical experiments involving 108 epithelial ovarian cancer samples." (PMID 31285390, 2019). "In summary, RRBP1 is overexpression in most epithelial ovarian cancer patients, and overexpression of RRBP1 in epithelial ovarian cancer leads to an even worse prognosis in patients with epithelial ovarian cancer." (PMID 31285390, 2019). "Further verification of the possibility of RRBP1 as an independent tumor biomarker is also necessary for epithelial ovarian cancer." (PMID 31285390, 2019). "RRBP1 is an independent prognostic factor for epithelial ovarian cancer." (PMID 31285390, 2019). "Therefore, it is very valuable to explore the impact of RRBP1 on the diagnosis and prognosis of ovarian cancer." (PMID 31285390, 2019). "The expression of RRBP1 in epithelial ovarian cancer tissues was analyzed by immunohistochemistry." (PMID 31285390, 2019). "In addition, our data showed that epithelial ovarian cancer patients with RRBP1 overexpression had significantly decreased OS and DFS." (PMID 31285390, 2019). "Univariate analysis showed that the prognosis of the epithelial ovarian cancer patients was related to the age of the patients, the FIGO stage, and the expression level of RRBP1 (P<0.05)." (PMID 31285390, 2019). "The difference in RRBP1 expression between epithelial ovarian cancer tissues and normal tissues was evaluated by Western blotting experiments and Real-time PCR." (PMID 31285390, 2019). "To assess whether the prognosis prediction ability of RRBP1 expression is independent of other clinicopathological features of patients with epithelial ovarian cancer, we performed multivariate Cox regression analysis." (PMID 31285390, 2019).
glioma (1 paper, 2025). A benign or malignant brain and spinal cord tumor that arises from glial cells (astrocytes, oligodendrocytes, ependymal cells). "In the Glioma/NC group, 8 proteins (COL1A1, PRL, VWF, HBD, SF3B1, NME3, RRBP1, and CSRP1) were selected, with an AUC of 0.892 in the training set and 0.871 in the validation set (accuracy: 78.5%)." (PMID 39716938, 2025).
Hyperkalemia (1 paper, 2023). An abnormally increased potassium concentration in the blood. "RRBP1-deficient mice manifested clinical features of hyporeninemic hypoaldosteronism, leading to lower blood pressure, severe hyperkalemia, and sudden cardiac death." (PMID 36803854, 2023). "The sudden death events of Rrbp1-KO mice associated with hyperkalemia were furthered validated by exposing mice to a 30-day high K+ intake, during which the sudden death events of Rrbp1-KO mice increased dramatically." (PMID 36803854, 2023). "RRBP1 deficiency in mice caused hyporeninemic hypoaldosteronism, resulting in lower blood pressure, severe hyperkalemia, and sudden cardiac death." (PMID 36803854, 2023). "Transgenic mice experiments showed that RRBP1 deficiency caused volume-related lower blood pressure and severe hyperkalemia-induced sudden cardiac death." (PMID 36803854, 2023). "Rrbp1- knockout (KO) mice had lower blood pressure and were more likely to die suddenly from severe hyperkalemia caused by phenotypically hyporeninemic hypoaldosteronism than wild-type controls." (PMID 36803854, 2023). "RRBP1 deficiency causes hyporeninemic hypoaldosteronism and hyperkalemia." (PMID 36803854, 2023). "Rrbp1-KO mice showed hyperkalemia with reduced urine K+ excretion, indicating defective renal tubular K+ secretion; they were, however, phenotypically corrected by fludrocortisone, suggesting hypoaldosteronism rather than pseudo-hypoaldosteronism." (PMID 36803854, 2023). "The terminal ECG of Rrbp1-KO mice was consistent with severe hyperkalemia, as shown by flattened P waves, widened QRS complexes, and a tall T wave, followed by asystole." (PMID 36803854, 2023). "Compared to Rrbp1-WT mice, the T waves of two Rrbp1-KO mice in the high K+ intake group peaked, which indicates severe hyperkalemia." (PMID 36803854, 2023). "Rrbp1-KO mice displayed features typical of hyporeninemic hypoaldosteronism with hyperkalemia, which could be ameliorated by fludrocortisones." (PMID 36803854, 2023).
invasive breast carcinoma (1 paper, 2012). A carcinoma that infiltrates the breast parenchyma. "We found RRBP1 as a novel candidate marker that is significantly overexpressed in invasive breast carcinomas." (PMID 22709790, 2012).
lung adenocarcinoma (1 paper, 2022). A carcinoma that arises from the lung and is characterized by the presence of malignant glandular epithelial cells. "Concordantly, both RRBP1 expression and USP35 expression were found to positively correlate with poor prognoses in lung adenocarcinoma patients." (PMID 34618999, 2022). "Moreover, as the well‐characterized ER stress‐related protein GRP78 has been reported to be closely related to the prognosis of lung adenocarcinoma patients, we therefore investigated the correlation of USP35 and RRBP1 with GRP78 in the public database GEPIA." (PMID 34618999, 2022). "Finally, positive correlation between USP35 and RRBP1 in human NSCLC tissues, as well as positive correlation between USP35 or RRBP1 and shorter overall survival of lung adenocarcinoma patients was confirmed." (PMID 34618999, 2022).
metastatic cancer (1 paper, 2022). A carcinoma which has spread from the original site of growth to another anatomic site. "Therefore, depletion of RRBP1 with shRRBP1 in bone metastatic cancer cells could boost the osteoblastic phenotype expression and ameliorate the bone lesions, partially via the enhancement of ER stress." (PMID 36568157, 2022).
pancreatic cancer (1 paper, 2026). "For RRBP1-ALK/Raf1 fusion proteins arising in EIMS and pancreatic cancer, selective kinase inhibitors can impair aberrant kinase activity but must be optimized to overcome RRBP1-mediated drug resistance." (PMID 41200062, 2026).
prostatic adenocarcinoma (1 paper, 2022). "The expression levels of RRBP1 in breast and prostatic adenocarcinoma tumor tissues were analyzed via Gene Expression Profiling Interactive Analysis (GEPIA) database." (PMID 36568157, 2022).
schistosomiasis (1 paper, 2015). An infectious disease caused by parasitic trematodes of the genus Schistosoma that colonize human blood vessels and release eggs that can cause granulomatous reactions leading to acute (swimmer's itch or acute schistosomiasis syndrome) or chronic disease. "It should also be noted that ribosome-binding protein 1 was one of the two antigens recognized by both S. mansoni-exposed PR subjects in Brazil and S. haematobium-exposed DIR subjects in Africa, possibly highlighting a common role in different mechanisms of schistosomiasis resistance." (PMID 25999951, 2015).
Upper Tract Urothelial Carcinoma (1 paper, 2021). "However, the correlation between RRBP1 expression and the prognosis of patients with upper tract urothelial carcinoma (UTUC) remains unclear." (PMID 34445467, 2021).
tumor (14 papers, 2016 to 2026). "Clinicopathological analysis has demonstrated that high RRBP1 expression is markedly and positively associated with the depth of tumor infiltration, LNM and advanced TNM stage." (PMID 41200062, 2026). "An analysis of the TCGA BC database revealed that RRBP1 is an oncogene associated with poor prognosis and is highly expressed in advanced and lymphatically metastatic tumor tissues." (PMID 39981244, 2025). "A comparable up-regulation of RRBP1 protein expression has been reported in tumor cells, where it has been linked to elevated mRNA levels resulting from gene amplification and/or increased transcriptional activity." (PMID 40663520, 2025). "In these reports, the enhancement of RRBP1 protein expression in tumor cell is attributed to the increase RRBP1 mRNA caused by gene amplification and/or the raise of transcription." (PMID 27447629, 2016). "One possible explanation is that certain mutations in RRBP1 may impair its function in protein transport and, therefore, slow tumor progression or they may occur in molecular subtypes that are intrinsically associated with a more favorable prognosis." (PMID 41200062, 2026). "Although its upregulation is closely associated with tumor progression, metastasis and chemotherapy resistance, its mechanistic basis reveals environment-dependent regulatory mechanisms; therefore, RRBP1 is a highly promising therapeutic target across cancer types." (PMID 41200062, 2026). "High RRBP1 expression is associated with tumor invasion and metastasis." (PMID 34445467, 2021). "Furthermore, in a UTUC patient-derived organoid model, high expression levels of RRBP1 have been associated with chemoresistance to cisplatin, gemcitabine and epirubicin; therefore, it synergistically promotes tumor cell survival by modulating ERS and yes-associated protein 1 (YAP1) signaling." (PMID 41200062, 2026). "RRBP1 is involved in tumor progression, has utility as a prognostic marker, is a driver gene in CRC and its expression level is also closely associated with chromosomal abnormalities." (PMID 41200062, 2026). "In summary, RRBP1 drives tumor malignant progression in high glucose environments through the E2F1/RRBP1 signaling axis and E2F1 directly binds RRBP1, and enhances its transcriptional activity, thereby promoting HCC cell proliferation, migration and invasion." (PMID 41200062, 2026). "RRBP1 is also associated with the unfolded protein response (UPR), a central mechanism through which tumor cells respond to ER stress (ERS)." (PMID 41200062, 2026). "Patients with high (≥8) Gleason scores have higher RRBP1 expression levels in tumor tissues compared with low Gleason scores." (PMID 41200062, 2026). "Future research can prioritize functional stratification of the RRBP1 network by using spatial multi-omics to determine how organelle communication is rewired in specific tumor subtypes." (PMID 41200062, 2026). "RRBP1-RNA interactions have further revealed the complex roles of RRBP1 in the regulation of tumor adaptation." (PMID 41200062, 2026). "They discovered that tumor organoids treated with cisplatin, gemcitabine, and epirubicin exhibited reduced reactivity to chemotherapy when RRBP1 expression was higher." (PMID 39981244, 2025). "The results showed a significantly higher expression of RRBP1 in tumor tissues(T), compared with normal tissues(N)." (PMID 36568157, 2022). "The methylation of the promoter region of the RRBP1 gene in normal tissue and tumor tissue was compared." (PMID 34445467, 2021). "CpG island methylation of RRBP1 in cancer cell lines was also confirmed, and RRBP1 was found to be hypomethylated in tumor cells." (PMID 34445467, 2021). "The examination of clinical samples also revealed the hypomethylation of RRBP1 in UTUC tumor tissues, while tumor cells that highly expressed RRBP1 displayed a high tolerance to clinical drugs." (PMID 34445467, 2021).
tumor (continued). "The level of RRBP1 is also related to the signal transduction of cell proliferation regulated by GRP78 or E2F, indicating the importance of RRBP1 as a tumor marker and possibly as a therapeutic target for the inhibition of cancer cell growth." (PMID 34445467, 2021). "Expression of RRBP1 in tumor samples was further analyzed, with protein expression detected by immunohistochemistry (IHC)." (PMID 34445467, 2021). "Even so, few studies have explored the mechanism by which RRBP1 regulates tumor cell growth, and its current functions are mainly related to ER pressure control." (PMID 34445467, 2021). "The expression of RRBP1 in tumor tissues (N0, N1, and N2) was significantly higher than that in normal tissues (p < 0.001)." (PMID 34445467, 2021). "We found that RRBP1 is overexpressed in EC patients, and its expression is correlated with tumor progression and poor survival." (PMID 30684972, 2019). "In some reports, the increase in RRBP1 protein expression in tumor cells is attributed to increased RRBP1 mRNA due to gene amplification and/or elevated transcription." (PMID 31285390, 2019). "Meanwhile, it has been reported that overexpression of RRBP1 protein reduced ER stress and enhanced cell survival in some tumor cell lines." (PMID 27447629, 2016). "Recently, some researchers reported the increase expression of RRBP1 protein in some tumor cells, indicated the great role of RRBP1 for survival, malignancy maintenance, and adaptation to ER stress in tumor cells." (PMID 27447629, 2016). "RRBP1 influences tumor metabolic reprogramming and microenvironmental adaptation by dynamically regulating substance transport and signaling between subcellular compartments and therefore might have translational value as a potential therapeutic target." (PMID 41200062, 2026). "Therefore, targeting RRBP1 or its downstream effector pathways can reverse malignant tumor phenotypes." (PMID 41200062, 2026). "By contrast, upregulation of RRBP1 enhances the anti-apoptotic ability of tumor cells." (PMID 41200062, 2026). "Therefore, inhibition of the METTL3/m6A axis, such as with small molecule peptides, decreases the stability of RRBP1 and blocks tumor progression." (PMID 41200062, 2026). "Although several studies have shown that the enhanced RRBP1 expression in tumor cells is attributed to its transcriptional and translational activation, nothing is known about whether RRBP1 can be regulated at post‐translational level." (PMID 34618999, 2022). "The expression level of RRBP1 was relatively high in tumor tissues." (PMID 34445467, 2021). "Low methylation in the RRBP1 genome was found in the tumor samples of UTUC." (PMID 34445467, 2021). "Tumor organoids with low RRBP1 expression appeared to be more chemosensitive." (PMID 34445467, 2021). "Expression of RRBP1 was high in tumor tissues with advanced stage and lymphatic metastasis." (PMID 34445467, 2021). "The methylation of the RRBP1 gene in tumor tissue was low compared to that in normal tissue." (PMID 34445467, 2021). "Moreover, there are already data showing that RRBP1 plays an important role in the survival of tumor cells, the maintenance of malignant tumors and the adaptation of ER stress." (PMID 31285390, 2019). "Therefore, it is speculated that RRBP1 may promote tumor growth and antichemotherapy drugs by regulating UPR-mediated autophagy during ER stress." (PMID 34445467, 2021). "In addition, RRBP1 is associated with tumor cell growth and resistance to the unfolded protein response (UPR), which might be an important milestone in tumor management and a potential prognostic biomarker for tumors." (PMID 34445467, 2021). "Hsa_circ_0004085 inhibits chemotherapeutic drug-induced ERS-associated apoptosis by enhancing the stability of GRP78 mRNA by binding RRBP1 and upregulating the expression level of GRP78, thus promoting chemoresistance in tumor cells." (PMID 41200062, 2026).